COX7B2 (cytochrome c oxidase subunit 7B2)
Description:
Component of the cytochrome c oxidase, the last enzyme in the mitochondrial electron transport chain which drives oxidative phosphorylation. The respiratory chain contains 3 multisubunit complexes succinate dehydrogenase (complex II, CII), ubiquinol-cytochrome c oxidoreductase (cytochrome b-c1 complex, complex III, CIII) and cytochrome c oxidase (complex IV, CIV), that cooperate to transfer electrons derived from NADH and succinate to molecular oxygen, creating an electrochemical gradient over the inner membrane that drives transmembrane transport and the ATP synthase. Cytochrome c oxidase is the component of the respiratory chain that catalyzes the reduction of oxygen to water. Electrons originating from reduced cytochrome c in the intermembrane space (IMS) are transferred via the dinuclear copper A center (CU(A)) of subunit 2 and heme A of subunit 1 to the active site in subunit 1, a binuclear center (BNC) formed by heme A3 and copper B (CU(B)). The BNC reduces molecular oxygen to 2 water molecules using 4 electrons from cytochrome c in the IMS and 4 protons from the mitochondrial matrix.
Tractability: Antibody: UniProt predicts a signal peptide or a membrane-spanning region.
Gene: Protein-coding gene on chromosome 4 (46,734,827 to 46,909,245, reverse strand). Ensembl gene ENSG00000170516.
Subcellular location: Mitochondrion inner membrane
Gene Ontology:
Biological process: mitochondrial electron transport, cytochrome c to oxygen; oxidative phosphorylation
Cellular component: mitochondrion; mitochondrial inner membrane; respiratory chain complex IV; membrane
Genetic constraint (gnomAD): Loss-of-function variants: 2 observed, 2.8 expected, observed/expected ratio (o/e) 0.71, 90% interval 0.28 to 1.77. That is too few expected variants to judge how well the gene tolerates losing a copy. Missense variants: 109 observed, 101.49 expected, observed/expected ratio (o/e) 1.07, 90% interval 0.92 to 1.26. Synonymous variants: 37 observed, 33.1 expected, observed/expected ratio (o/e) 1.12, 90% interval 0.86 to 1.47.
Homologues: Orthologues: chimpanzee COX7B2 (99% identical), dog COX7B2 (73% identical), pig COX7B2 (69% identical), rat Cox7b2 (60% identical), mouse Cox7b2 (59% identical), tropical clawed frog cox7b (54% identical). Paralogues in human: COX7B (69% identical).
Diseases named in the same sentence as COX7B2 in open-access papers:
COX7B2 is named in the same sentence as 9 diseases in open-access papers, as found by Europe PMC text mining. Sharing a sentence is not in itself a finding about the gene and the disease. The quoted sentences say what the papers report.
Alzheimer disease (1 paper, 2019). A progressive, neurodegenerative disease characterized by loss of function and death of nerve cells in several areas of the brain leading to loss of cognitive function such as memory and language. "Finally, in the broader context of traits potentially related to cognition, we find an enrichment of HHMCs in genes associated to “Alzheimer’s disease (cognitive decline)” and “Cognitive decline (age-related)”, with seven associated genes (COX7B2, BCAS3, DMXL1, LIPC, PLEKHG1, TTLL2 and VIT)." (PMID 31186485, 2019).
nonalcoholic fatty liver disease (1 paper, 2021). "Out of 482 positional candidate genes, 2 genes at Fmgq2 are found on metabolically relevant KEGG pathways: Srd5a3 (steroid hormone biosynthesis; mmu00140) and Cox7b2 (nonalcoholic fatty liver disease; mmu004932)." (PMID 33723359, 2021).
Parkinson disease (1 paper, 2019). A progressive degenerative disorder of the central nervous system characterized by loss of dopamine producing neurons in the substantia nigra and the presence of Lewy bodies in the substantia nigra and locus coeruleus. "In the present study, we also detected that five DEmRNAs, including COX7B2, UBA1Y, VAT1, CYCT and SLC6A3, were enriched in the pathway of Parkinson’s disease." (PMID 31447646, 2019).
COX7B2 also shares sentences with these, for which no sentence is quoted: cancer (2 papers); asthenozoospermia (1); breast carcinoma (1); Cognitive decline (1); neurodegenerative disease (1); type 2 diabetes (1).